BLVRB (biliverdin reductase B)
Diseases named in the same sentence as BLVRB in open-access papers:
BLVRB is named in the same sentence as 56 diseases in open-access papers, as found by Europe PMC text mining. Sharing a sentence is not in itself a finding about the gene and the disease. The quoted sentences say what the papers report.
hepatocellular carcinoma (6 papers, 2020 to 2023). A malignant tumor that arises from hepatocytes. "The proliferation of hepatocellular carcinoma cells is inhibited by the knockdown of BLVRB, which is regulated by LNC_000204." (PMID 34368149, 2021). "miR-127 also decreases the phosphorylation of p65 and the expression of downstream targets of the NF-κB signaling pathway, and inhibits the growth and colony formation of hepatocellular carcinoma cells through decreasing BLVRB expression." (PMID 32979257, 2020). "Further study showed that the mir‐127‐5p could inhibit the proliferation and clone formation of hepatoma cells, and also prohibit the expression of the target gene, biliverdin reductase B (BLVRB), by directly binding with 3′UTR." (PMID 33880887, 2021). "Higher BLVRB expression compared to normal tissues has been reported in numerous types of cancer, including esophageal carcinoma, acute lymphoblastic leukemia, hepatocellular carcinomas (HCC), endometrial carcinoma, prostate cancer, pancreatic cancer, and vaginal and breast cancer." (PMID 37237924, 2023). "In hepatocellular carcinoma (HCC), the restoration of BLVRB impairs the suppression of HCC growth by miR-127-5p16." (PMID 35517415, 2022).
breast carcinoma (5 papers, 2018 to 2025). "Consistent with gradual expression during oncogenesis, BLVRB was shown to be associated with tumor progression in cultured cells from defined breast cancer stages and different stages of human breast cancer specimens." (PMID 37237924, 2023). "In addition, BLVRB lymphatic expression is associated with the presence of metastases in a mouse model of breast cancer." (PMID 37237924, 2023). "Integrated proteomic, metabolomic, and lipidomic studies identified and validated BLVRB-mediated adaptive metabolic responses required for breast cancer cell cytoprotection." (PMID 40470256, 2025). "This study, along with our recent progress in developing novel specific BLVRB inhibitors, offers a unique translational opportunity for targeted therapies in personalized breast cancer medicine." (PMID 40470256, 2025). "Various studies focusing on the development of blood-based biomarkers have identified elevated BLVRB in the serum of cancer patients compared to healthy controls, including pancreatic and breast cancer cohorts." (PMID 37237924, 2023). "Human BLVRB was also shown to be an NRF2 target gene: both KEAP1 knockdown and treatment with 15 μM sulforaphane induced BLVRB transcripts one- to threefold in breast cancer MCF10A cells." (PMID 28793787, 2018). "BLVRB overexpression has been observed in breast cancers, although its function in breast cancer pathogenesis remains unknown." (PMID 40470256, 2025). "Furthermore, BLVRB has been detected in the exosomes of tumor-draining lymph comparing metastatic to non-metastatic tumors in a murine breast cancer model." (PMID 37237924, 2023). "Using a proteomic approach, we could show that several antioxidant proteins, for example, SOD1, PRDX2, and PARK7, were downregulated in the normo-sensitive patients and some antioxidant proteins, for example, BLVRB and PRDX2, were upregulated in the radiosensitive breast cancer patients." (PMID 29951164, 2018).
prostate carcinoma (4 papers, 2019 to 2025). A carcinoma that arises from epithelial cells of the prostate gland. "Detected overexpression of biliverdin reductase-B, which is a redox enzyme in prostate cancer samples, thus taking it as a new biomarker type with implications for oxidative stress regulation in tumors." (PMID 41228317, 2025). "In addition, BLVRB has been detected in prostate cancer tissue samples (but not normal prostate) and in body fluids (urine, bladder washing samples, semen samples) isolated from prostate cancer patients." (PMID 37237924, 2023).
carotid atherosclerosis (2 papers, 2023). A thickening and loss of elasticity of the walls of carotid arteries that occur with formation of atherosclerotic plaques. "Biliverdin reductase B (BLVRB) was found to be enriched in both plaques and plasma of patients with carotid atherosclerosis, particularly associated with intraplaque haemorrhage (IPH)." (PMID 39802625, 2023). "Biliverdin reductase B (BLVRB) is enriched in plasma and plaques from patients with symptomatic carotid atherosclerosis and functionally associated with IPH." (PMID 37371462, 2023). "BLVRB was enriched in plaques and plasma from patients with symptomatic carotid atherosclerosis and was also found to be elevated in a larger cohort of patients with coronary artery disease." (PMID 37371462, 2023). "However, the association of plasma BLVRB with clinically identified IPH, or with stroke risk in patients with carotid atherosclerosis has yet to be established." (PMID 37371462, 2023).
endometrial carcinoma (2 papers, 2023 to 2024). A malignant tumor arising from the epithelium that lines the cavity of the uterine body. "In endometrial carcinoma, BLVRB is highly expressed primarily at the invasive front of tumors, suggesting its potential involvement in progression and invasion." (PMID 37237924, 2023).
pancreatic cancer (2 papers, 2020 to 2023). "Furthermore, based on data reported in the Human Protein Atlas database, AP2A2, PLST, PLSI, BLVRB and SLC2A1 were associated with poor 5-year overall survival in pancreatic cancer." (PMID 33048956, 2020).
atherosclerosis (1 paper, 2023). A disease characterized by the build-up of fatty material and calcium deposition in the arterial wall resulting in partial or complete occlusion of the arterial lumen. "In a similar manner to human atherosclerosis, BLVRB and its upstream enzyme in Hb catabolism, HMOX1, were also expressed in regions of CD68-positive macrophages in atherosclerotic mouse vein grafts." (PMID 37371462, 2023). "Furthermore, to evaluate the capacity of BLVRB to monitor pharmacotherapeutic effects specifically targeting IPH, plasma BLVRB levels were assessed in a preclinical atherosclerotic mouse vein graft model of unstable atherosclerosis subject to antiangiogenic treatment targeting IPH." (PMID 37371462, 2023).
Bell's palsy (1 paper, 2025). Partial or complete paralysis of the facial muscles of one side of a person's face. "In this study, 70 inflammation-related proteins that may be causally associated with Bell’s palsy were identified by MR analysis, and 7 significantly related proteins were screened by external dataset validation, including BLVRB, HMOX2, TNFRSF12A, DEFB128, ITM2A, DDX58 and VEGF-A." (PMID 40299566, 2025). "In our study, BLVRB and VEGF-A as potential protective factors in Bell’s palsy may contribute to the reduction in Bell’s palsy." (PMID 40299566, 2025).
breast tumor (1 paper, 2015). "Five genes (SEMA3F, BLVRB, PTPRF, MARCKS, and CQQ6) are up regulated both in HER2 positive cell lines and in high HER2 expressing primary breast tumor tissues." (PMID 25428913, 2015).
coronary artery calcification (1 paper, 2023). Calcification of the coronary artery, used as a measure of coronary atherosclerosis, a risk factor for myocardial infarction. "Previously, we reported elevated plasma BLVRB levels in patients with symptomatic vs. asymptomatic carotid stenosis, as well as an association with increasing coronary atherosclerosis as stratified by coronary artery calcification scoring." (PMID 37371462, 2023).
COVID-19 (1 paper, 2023). A disease caused by infection with severe acute respiratory syndrome coronavirus 2. "By excluding 4 genes, YBX3, RBM38, ANCA, and BLVRB, with opposite expression trends, we found that when compared to control samples, practically all of these genes showed persistently high expression in AMI and COVID-19." (PMID 38022594, 2023).
influenza infections (1 paper, 2016). "BLVRB, biliverdin reductase B, is according to FANTOM5 expressed in CD34 + cells, as well as in whole blood and in monocyte-derived macrophages responding to certain influenza infections and in bronchial epithelial cells." (PMID 27632927, 2016).
Insulin resistance (1 paper, 2025). Increased resistance towards insulin, that is, diminished effectiveness of insulin in reducing blood glucose levels. "More investigations are needed about the regulatory factors that control BLVRA and BLVRB expression and the bilR bacterial enzyme and their functional roles in fatty liver, MASLD, insulin resistance, insulin clearance, and T2DM." (PMID 39873298, 2025).
intracranial hemorrhage (1 paper, 2025). Bleeding within the SKULL, including hemorrhages in the brain and the three membranes of MENINGES. "Therefore, LEF1, BLVRB, ITGAX and ATF4 are expected to become new biomarkers for intracranial hemorrhage." (PMID 40933575, 2025).
ischemic stroke (1 paper, 2023). A stroke disorder caused by obstruction of blood flow to the brain, due to thrombotic (local blood clot formation) or embolic (due to a blood clot or other material traveling from another site) event. "However, plasma BLVRB levels significantly associated with the combined endpoint of recurrent ischemic stroke and TIA after excluding AFX (HR = 1.469, CI [1.094–1.974]; p = 0.011, adjusted for age and gender; p = 0.038)." (PMID 37371462, 2023). "First, in a clinical setting, we demonstrated that plasma BLVRB levels were associated with the presence of IPH in patients with symptomatic, low- to moderate-grade carotid stenosis and with recurrent ischemic stroke during a 5 year follow-up." (PMID 37371462, 2023). "The aim of this study was, therefore, to explore the biomarker potential of BLVRB by evaluating the relationship between plasma BLVRB levels and the clinical presence of IPH, as well as the incidence of recurrent ischemic stroke in patients with symptomatic carotid stenosis." (PMID 37371462, 2023). "Of note, 36.4% of the patients who developed a recurrent ischemic stroke did not have an IPH detected by MRI (data not shown), suggesting a higher precision of BLVRB plasma levels in predicting recurrent ischemic strokes compared with IPH detected by MRI." (PMID 37371462, 2023). "Stratification of the secondary endpoint to associate plasma BLVRB levels with recurrent ischemic stroke, TIA, or AFX separately showed that plasma BLVRB levels were significantly predictive of recurrent ischemic stroke ( p = 0.016) but not recurrent TIA (p = 0.213) or recurrent AFX (p = 0.225)." (PMID 37371462, 2023).
liver cancer (1 paper, 2024). An epithelial or non-epithelial malignant neoplasm that arises from the liver. "Additionally, heme degradation enzymes displayed an interesting contrasting pattern of isozyme BLVRA and BLVRB gene expression, indicating that normal hepatocytes and liver cancer lines utilize different processes for heme degradation." (PMID 39199347, 2024).
liver fibrosis (1 paper, 2017). "Furthermore, CAT, BLVRB, NXN, PRDX1, and IDH1 may be candidates for the detection of liver fibrosis or therapeutic targets for the treatment of liver fibrosis." (PMID 28830339, 2017). "Furthermore, CAT, BLVRB, NXN, PRDX1, and IDH1 may be candidates for detection of liver fibrosis or therapeutic targets for the treatment of liver fibrosis." (PMID 28830339, 2017).
lymph node metastasis (1 paper, 2022). "Prognostic clinical data showed that low expression BLVRB was associated with poor prognosis and lymph node metastasis." (PMID 35517415, 2022). "A low BLVRB expression level was strongly associated with lymph node metastasis (P = 0.016)." (PMID 35517415, 2022). "Therefore, BLVRB levels seem to be negatively associated with lymph node metastasis." (PMID 35517415, 2022).
migraine (1 paper, 2022). "The expression levels of various key proteins and metabolites, including α-D-glucose, flavin adenine dinucleotide, biliverdin reductase B, and L-glutamate, were significantly differentially expressed before and after acupuncture treatment in patients with migraine without aura." (PMID 36248663, 2022).
Stroke (1 paper, 2023). Sudden impairment of blood flow to a part of the brain due to occlusion or rupture of an artery to the brain. "Here, we evaluated the association between BLVRB levels and future risk of stroke." (PMID 37371462, 2023).
Thrombocytopenia (1 paper, 2024). A reduction in the number of circulating thrombocytes. "This discovery opens new avenues for investigating the roles of BLVRB in blood disorders, including thrombocytopenia." (PMID 39339186, 2024). "Biliverdin IXβ reductase (BLVRB) has emerged as a promising therapeutic target for thrombocytopenia due to its involvement in reactive oxygen species (ROS) mechanisms." (PMID 39339186, 2024).
cancer (8 papers, 2016 to 2024). A tumor composed of atypical neoplastic, often pleomorphic cells that invade other tissues. "However, there has been limited evidence on the association of BLVRB proteins and their possible pro-carcinogenic mechanism in cancers." (PMID 37501157, 2023). "Evidence supporting the pathophysiological significance of BLVRB in cancer originates predominantly from unbiased proteomics and gene expression profiling." (PMID 37237924, 2023). "An extension of these observations further suggests that BLVRB inhibition represents an ancillary strategy for modulating cellular glutamine utilization, with putative interventional consequences for cancer and hematopoietic metabolism." (PMID 37237924, 2023). "Since BLVRB appears dispensable for normal organ development based on murine models, BLVRB-selective inhibitors have the potential to be cellular targets for modulating hematopoietic lineage speciation or as novel cancer therapeutics." (PMID 37237924, 2023). "To explore the mechanism by which BLVRB regulates CCA development, we identified genes whose expression patterns correlated with those of BLVRB in the Cancer Genome Atlas CCA dataset and performed gene set enrichment analysis (GSEA)." (PMID 35517415, 2022). "Collectively, these observations implicate BLVRB expression with tumor aggression, either as a consequence or adaptive mechanism for enhancing antioxidant defense pathways in proliferative and invasive cancers." (PMID 37237924, 2023). "Since cancer cells reside in hypoxic niches and rely on glutamine metabolism for survival and growth, BLVRB-selective redox inhibitors may have synergistic anti-cancer effects on both cytoprotective loss and glutamine utilization." (PMID 37237924, 2023). "Additionally, targeting BLVRB activity in cancer cells could disrupt their metabolism and sensitize them to metabolic inhibitors, while in other contexts increasing BLVRB expression may suppress the epithelial–mesenchymal transition, offering a strategy to prevent metastasis." (PMID 39768998, 2024).
tumor (5 papers, 2022 to 2025). "According to the RT-PCR analysis, BLVRB was markedly lower in tumor tissues compared to peritumor tissues (P < 0.001)." (PMID 35517415, 2022). "We conclude that BLVRB suppression promotes Notch activity, which is important for tumor cell dissemination." (PMID 35517415, 2022). "Genetic studies have shown that the knockdown of BLVRB-mediated Notch signaling affects tumor cell migration and invasion in CCA." (PMID 35517415, 2022). "Interestingly, it was reported that overexpression of BLVRB indicates the early stage of tumor development which highlights the role of hypoxia condition in the tumor induction." (PMID 37501157, 2023). "BLVRB levels were lower in tumor tissues than in peritumor tissues." (PMID 35517415, 2022).
infection (2 papers, 2009 to 2022). The state of being infected such as from the introduction of a foreign agent such as serum, vaccine, antigenic substance or organism. "Biliveridin reductase a and b (BLVRA and BLVRB) and Heme oxygenase (HMOX1) are involved in degradation of erythrocytes and both Blvra and Blvrb expression increased 2–4 fold in the liver by day 9 post infection." (PMID 19365556, 2009).
BLVRB also shares sentences with these, for which no sentence is quoted: anemia (2 papers); Parkinson’s (2); apraxia (1); blood disorders (1); cervical squamous cell carcinoma (1); cholangiocarcinoma (1); cognitive deficit (1); colorectal cancer (1); Congenital hemolytic anemia (1); coronary atherosclerosis (1); dementia (1); Dystonia (1); endometriosis (1); endothelial dysfunction (1); focal dystonia (1); head and neck cancer (1); hereditary spherocytosis (1); liver cirrhosis (1); lung carcinoma (1); lymphoma (1); neuroblastoma (1); Obesity (1); osteosarcoma (1); prostate (1); prostate adenocarcinoma (1); psychiatric disorder (1); rheumatoid arthritis (1); sarcoma (1); schizophrenia (1); stomach cancer (1).
A further 2 diseases each share a sentence with BLVRB in 1 paper.